KMT2E-AS1 (KMT2E antisense RNA 1)
Synonyms: lncPENG; LOC100216545; RP11-325F22.5.1; LHFPL3-AS2; LINC01004
Gene: Long non-coding RNA gene on chromosome 7 (104,894,628 to 105,014,321, reverse strand). Ensembl gene ENSG00000239569.
Gene Ontology:
Biological process: SRP-dependent cotranslational protein targeting to membrane, signal sequence recognition
Cellular component: signal recognition particle, endoplasmic reticulum targeting
Diseases named in the same sentence as KMT2E-AS1 in open-access papers:
KMT2E-AS1 is named in the same sentence as 5 diseases in open-access papers, as found by Europe PMC text mining. Sharing a sentence is not in itself a finding about the gene and the disease.
KMT2E-AS1 shares sentences with these, for which no sentence is quoted: tumor (2 papers); cancer (1); esophageal squamous cell carcinoma (1); hepatocellular carcinoma (1); liver cancer (1).